SAA1 (serum amyloid A1)
Description:
Major acute phase protein.
Synonyms: SAA; PIG4; TP53I4
Tractability: Antibody: UniProt places it where antibodies can reach, with high confidence; its Gene Ontology location is reachable by antibodies, with high confidence; UniProt predicts a signal peptide or a membrane-spanning region.
Gene: Protein-coding gene on chromosome 11 (18,266,260 to 18,269,977, forward strand). Ensembl gene ENSG00000173432.
Subcellular location: Secreted
Pathways (Reactome):
Immune System: Advanced glycosylation endproduct receptor signaling; Interleukin-4 and Interleukin-13 signaling; TAK1-dependent IKK and NF-kappa-B activation; TRAF6 mediated NF-kB activation
Signal Transduction: Formyl peptide receptors bind formyl peptides and many other ligands; G alpha (i) signalling events; G alpha (q) signalling events
Metabolism of proteins: Amyloid fiber formation
Vesicle-mediated transport: Scavenging by Class B Receptors
Gene Ontology:
Molecular function: G protein-coupled receptor binding
Biological process: lymphocyte chemotaxis; macrophage chemotaxis; positive regulation of cell adhesion; positive regulation of cytokine production; positive regulation of cytosolic calcium ion concentration; negative regulation of inflammatory response; neutrophil chemotaxis; platelet activation; positive regulation of interleukin-1 production; regulation of protein secretion
Cellular component: cytoplasmic microtubule; extracellular exosome; endocytic vesicle lumen; extracellular region
Genetic constraint (gnomAD): Loss-of-function variants: 6 observed, 9.14 expected, observed/expected ratio (o/e) 0.66, 90% interval 0.36 to 1.29. That is too few expected variants to judge how well the gene tolerates losing a copy. Missense variants: 114 observed, 137.25 expected, observed/expected ratio (o/e) 0.83, 90% interval 0.71 to 0.97. Synonymous variants: 47 observed, 54.76 expected, observed/expected ratio (o/e) 0.86, 90% interval 0.68 to 1.1.
Homologues: Orthologues: chimpanzee SAA1 (97% identical), macaque SAA1 (89% identical), macaque SAA2 (89% identical), zebrafish saa (58% identical), Drosophila melanogaster CG30467 (10% identical). Paralogues in human: SAA2 (93% identical), SAA4 (56% identical), SAAL1 (20% identical).
Diseases named in the same sentence as SAA1 in open-access papers:
SAA1 is named in the same sentence as 229 diseases in open-access papers, as found by Europe PMC text mining. Sharing a sentence is not in itself a finding about the gene and the disease. The quoted sentences say what the papers report.
COVID-19 (42 papers, 2020 to 2026). A disease caused by infection with severe acute respiratory syndrome coronavirus 2. "Here we have confirmed the proteomic results by western blot for AAT and SAA-1 that were clearly markedly associated with HDLs from COVID-19 patients." (PMID 33504824, 2021). "The observed change in the degree centrality score of SAA1 from 5 to 44 in ALI- and COVID-19-associated regulomes, respectively, demonstrates the expediency of further investigations into SAA1 as a probable marker of the severity of lung injury." (PMID 34807957, 2021). "SAA-1 was abundantly associated with HDLs isolated from COVID-19 patients relative to that of controls." (PMID 33504824, 2021). "On the other hand, SAA1 is increased on the HDL of COVID-19 patients in a manner that was associated with COVID-19 severity." (PMID 34638523, 2021). "Improved large-scale shotgun approaches combined with extensive fractionation have been applied to identify potential COVID-19 biomarkers and could be used in association with SAA1 and SAA2 provided in this study to create a panel of more reliable biomarkers." (PMID 34168074, 2021). "ROC curve analysis shows that SERPINA3 can distinguish influenza, COVID-19, mixed infection and healthy people; SAA1 can distinguish COVID-19, mixed infection and healthy people; SAA2 can distinguish influenza and healthy people." (PMID 40158620, 2026). "Several proteins linked to the acute phase response, such as CRP, SERPINA3, SAA1 and SAA2, have been shown to increase in the plasma of patients with severe COVID-19 using MS-based data-independent analysis." (PMID 40568587, 2025). "Proteomics studies showed the signatures of cytokine production and interferon-γ response, and increased levels of SAA1 in the serum of COVID-19 patients." (PMID 35438176, 2022). "The clear association of SAA1 with MDD and its persistent high concentration in severe COVID-19 (+) patients suggests that a closer look at its relationship with post-COVID depression is needed." (PMID 34575258, 2021). "Conversely, other proteins were found to be more abundant in HDLs from COVID-19 patients, such as SAA-1 and 2, alpha-1 antitrypsin (AAT) and alpha-1 acid glycoprotein 1, considered as acute phase proteins." (PMID 33504824, 2021). "There was a significant difference in PPP SAA1 concentrations between controls and acute COVID-19 (p = 0.02), and controls and Long COVID/PASC (p = 0.003)." (PMID 34425843, 2021). "The concentration distribution of SAA1 were as follows: for controls (3.0 mg L−1 (± 0.9)), acute COVID-19 (3.7 mg L−1 [3.3—5.4]) and Long COVID/PASC (3.98 mg L−1 (± 0.43)." (PMID 34425843, 2021). "Western-blot analysis was performed on selected proteins in order to confirm mass spectrometry identification and abundance comparison between COVID-19 and control conditions: SAA-1, PON-1 and AAT." (PMID 33504824, 2021). "We identified 5 proteins that were significantly more abundant in HDLs from COVID-19 patients, namely serum amyloid A-1 and 2 (SAA-1, 2), alpha-1 anti-trypsin (AAT), fibrinogen beta chain and alpha-1 acid glycoprotein." (PMID 33504824, 2021). "MALDI-TOF analysis revealed differential plasma levels of SAA1 and SAA2 associated with higher risk of hospitalization and can be used to improve COVID-19 monitoring and therapy." (PMID 34168074, 2021). "We further identified strong genetic correlations (|r| > 0.5) between smaller sets of proteins related to COVID-19 severity, and host proteins relevant to viral replication such as between IL-6-induced proteins (SAA1, SAA2, and CD14) and fibulin 5 (FBLN5)." (PMID 33328453, 2020). "The ROC curve showed that SERPINA3 could only distinguish between influenza, COVID-19, Mix, and health; SAA1 could only distinguish between COVID-19, Mix, and health; and SAA2 could only distinguish between influenza and health." (PMID 40158620, 2026).
COVID-19 (continued). "It would be of interest to determine whether HDL enriched in SAA1 and depleted of ApoA1, as seen in patients with COVID-19 and other inflammatory diseases, may exhibit an altered ability to modify SARS-CoV-2 infection of target cells." (PMID 34638523, 2021). "HEP6 and HEP7 cells had similar profiles to those in the HEP2 subset but with high expression of acute phase proteins in HEP7 (e.g., CRP, C3, C4a, SAA1, and FTH1; a COVID-19 specific cluster; below) or apoptosis and cellular senescence pathways in HEP6." (PMID 40087773, 2025). "For these COVID-19 convalescents, we found higher plasma concentrations of CRP, SAA1, and SAA2 six months after COVID-19." (PMID 39183264, 2024). "We found that the expression levels of inflammation-related proteins (CRP, SAA1, SAA2, and ORM1) were substantially elevated in the acute phase of COVID-19, consistent with the proteomic results." (PMID 38965561, 2024). "The inflammatory factors SAA2, SAA1, SERPINA1, and SERPINA3 are significantly upregulated proteins in the sera of the severe COVID-19 patients." (PMID 38638822, 2024). "When levels of host proteins were compared between COVID-19 and TB patients, five (ApoA1, CRP, ferritin, SAA1/A2, and S100A12) showed promising discriminatory potential as all but ApoA1 were significantly higher in COVID-19 patients’ sera." (PMID 36590898, 2023). "For CRP, ferritin, SAA1/A2, and S100A12, serum cytokine levels were significantly higher in the COVID-19 group (p<0 · 0001, p = 0 · 0038, p<0 · 0001 and p<0 · 0001, respectively)." (PMID 36590898, 2023). "Of note was that for six markers (CRP, ferritin, IL-6, IP-10, SAA1/A2, and S100A12) higher values were detected in COVID-19 sera whereas for ApoA1, significantly lower levels were detected in the COVID-19 group (p<0 · 0001)." (PMID 36590898, 2023). "We found that the plasma levels of HP, LTA4H, S100A9, SAA1, SAA2, and SERPINA3 were significantly elevated in more severe COVID-19 conditions, exhibiting good clinical predictive value and promising applications." (PMID 37197655, 2023). "ROC analysis showed ideal AUC values for SAA1 (0.912) and SAA2 (1.000) in patients with COVID-19-induced ARDS." (PMID 37197655, 2023). "For example, acute phase proteins (APPs) including serum amyloid A-1 (SAA1), SAA2, SAA4 and C-reactive protein (CRP) were increased in severe COVID-19 patients, indicating activation of inflammation and the complement system." (PMID 35686122, 2022). "SAA1, was about twofold increased in PPP from both acute COVID-19 and Long COVID/PASC as seen with an SAA1 ELISA." (PMID 34425843, 2021). "The SAA1 and SAA2 proteins were also identified up-regulated in severe COVID-19 patients in a clinical cohort from China." (PMID 34168074, 2021). "To determine whether SERPINA3, SAA1, and SAA2 can serve as biomarkers for influenza, COVID-19, and Mix, we classified the three genes." (PMID 40158620, 2026). "Validation of SERPINA3, SAA1, and SAA2 as biomarkers for influenza, COVID-19, and Mix." (PMID 40158620, 2026). "Serum amyloid A1 (SAA1) and serum amyloid A2 (SAA2), which were significantly upregulated in both the acute and subacute phases, have been reported to be severity-related biomarkers in ARDS due to COVID-19." (PMID 40375315, 2025). "For ApoA1, ferritin, IP-10, and SAA1/A2, no significantly different levels were observed at hospital admission – between COVID-19 patients with moderate disease, severe disease or fatal outcome." (PMID 36590898, 2023). "SAA1, a close family member, was also elevated by 2.8-fold in COVID-19 patients, although this elevation was not statistically significant." (PMID 36430724, 2022). "Nevertheless, for the COVID-19 patients, we did find clustering based on hospitalization status (ICU, ward, or discharge), showing that the main drivers of plasma proteomes (CRP, SAA1, and SAA2) can effectively function as clinical classifiers for disease severity." (PMID 40224277, 2025).
COVID-19 (continued). "Additionally, the acute phase proteins (CRP, SAA1 and SAA2) deviated from the linear correlation (R2 = 0.97) of the plasma proteome changes quantified in both genders, indicating a 3- to 6-fold difference in concentrations measured six months after COVID-19." (PMID 39183264, 2024). "Cluster 12 and 13 report proteins that are increased in all COVID-19 patients but at higher levels in ICU/F patients which are mainly constituted by proteins playing a role in acute inflammatory response (CRP, ORM1, ORM2, SAA1, SAA2, S100A8, S100A9, Serpin A3)." (PMID 36348270, 2022). "Interestingly, the listed genes reported as potent markers of critical illness in COVID-19 (CCL2, MMP8, IFI44, LCN2, SAA1) were identified by us as key regulators of both murine ALI and COVID-19-associated ARDS in human with the highest scores of degree centrality." (PMID 34807957, 2021). "We also observed that plasma from PLWH with COVID-19 had the greatest multiplicative increase in SAA2 (FC = 139.28) and SAA1 (FC = 110.40); however, this difference was not statistically significant after FDR correction." (PMID 40568587, 2025). "A number of proteins identified as outcome predictors have also been shown to be differentially expressed in sepsis, including SAA1, CRP, SERPINA1, KLKB1, and A2M, indicating a general inflammatory signature rather than specific markers of COVID-19." (PMID 36812516, 2022). "However, the observation frequency of CRP, AAT, FGA, S100, SAA1 and others was often greater in ICU-ARDs or COVID-19 compared to normals, therefore these proteins were not specific markers of COVID-19 infection but rather reflected lung damage." (PMID 37031181, 2023). "Moreover, most acute phase proteins, such as SAA1, SAA2, SAA4, CRP, SERPINA3, and SAP/APCS, which were increased in severe COVID-19 patients were not changed in our CoronaVac immunized samples." (PMID 35686122, 2022).
Sepsis (30 papers, 2014 to 2026). Sepsis is defined as life-threatening organ dysfunction caused by a dysregulated host response to infection. "This suggests sepsis-injured TECs release SAA1-carrying EVs that disseminate via circulation, delivering pathogenic SAA1 to distant recipient cells." (PMID 40936924, 2025). "For instance, exosomal SAA1 has been shown to be effective in treating lung injury caused by sepsis." (PMID 38540147, 2024). "Serum amyloid A1 (SAA1), a protein associated with inflammation and acute-phase responses during sepsis, which is secreted by the liver, but also by skeletal muscle, causes myocyte atrophy by activating the TLR2/TLR4/NF-κB/p65 signaling pathway." (PMID 36499366, 2022). "The acute-phase response protein serum amyloid A1 (SAA1) is associated with inflammation during sepsis." (PMID 34572540, 2021). "SAA1 is associated with muscle wasting in cancer cachexia and sepsis." (PMID 38533529, 2024). "Thus there was disease associated variation in the processing of SAA1 in ICU-Sepsis versus ICU controls or other diseases and controls." (PMID 32636717, 2020). "Importantly, SAA1 was identified as one of the most robust Zn-responsive genes in which case Zn deficiency augmented its expression whereas Zn supplementation decreased its expression in response to sepsis." (PMID 24732911, 2014). "Interestedly, the same pattern for SAA-1 was observed previously in plasma between sepsis and HLH patients." (PMID 41463121, 2025). "SAA1 plus several conventional biomarkers including C-reactive protein, procalcitonin are extensively investigated to diagnose sepsis." (PMID 40936924, 2025). "Collectively, our findings indicate that inflammation-driven SAA1 plays a key role in lethal sepsis pathogenesis by promoting caspase-11-mediated pyroptosis." (PMID 38297162, 2024). "Liver-specific activation of GR and the resultant synergistic induction of SAA1 will be beneficial for inflammatory liver diseases and sepsis." (PMID 39619227, 2023). "Earlier studies using a transgenic approach in mice with an inducible expression of human SAA1 in macrophages demonstrated protection against sepsis, LPS-induced inflammation, and acute lung injury." (PMID 38139330, 2023). "SAA-1 was more accurate in predicting early-onset sepsis than CRP (sensitivity (96 vs. 30%), specificity (95 vs. 98%)." (PMID 35329889, 2022). "They reported that SAA1 participates in a positive feedback loop of self-perpetuating inflammation in muscle during sepsis." (PMID 34572540, 2021). "The FN1, ITIH3, SAA1 and other peptides observed were consistent with previous claims of utility for these proteins as sepsis biomarkers." (PMID 32636717, 2020). "During sepsis, SAA1 is increased in muscle and directly acts on myocytes via the TLR2/TLR4/NF‐κB p65 axis." (PMID 31441598, 2020). "Tryptic peptides cleaved in plasma from SAA1 showed a higher observation frequency and/or mean log10 intensity in sepsis." (PMID 32636717, 2020). "Additional cleavages of SAA1 on the NH2 terminus side of the Cystatin Binding Site were observed in ICU-Sepsis." (PMID 32636717, 2020). "The observation frequency of peptides from SAA1 was much higher in ICU-Sepsis compared to any other disease of control treatment." (PMID 32636717, 2020). "Additional cleavage of SAA1 on the NH2 terminus side of the cystatin binding site were observed in ICU-Sepsis." (PMID 32636717, 2020). "RT-PCR analyses performed on the gastrocnemius plantaris and tibialis anterior confirmed increased muscular SAA1 expression during sepsis." (PMID 24651840, 2014). "We investigated factors regulating SAA1 synthesis in skeletal myocytes and tested conservation of this pathway in a sepsis mouse model." (PMID 24651840, 2014). "Several other studies have also pointed to acute-phase reactants, including SAA1, as sepsis biomarkers in multiple populations, constituting a consensus that these proteins may be useful for sepsis diagnosis." (PMID 40493423, 2025).